STAT3 (signal transducer and activator of transcription 3)
Diseases named in the same sentence as STAT3 in open-access papers (continued):
Sharing a sentence is not in itself a finding about the gene and the disease.
tumor (continued). "NF-κB and STAT3 are strictly involved in the control of apoptosis-based tumor-surveillance, tumor angiogenesis and invasiveness." (PMID 30441761, 2018). "In an effort to identify that tumor‐driven like macrophages secreted IL‐8 in a STAT3‐dependent mechanism, we examined the mRNA and protein expression level of IL‐8 followed by using STATTIC, a small molecule selective inhibitor of STAT3 pathway." (PMID 30311406, 2018). "In this latter work, they demonstrated that decoy-based targeted inhibition of STAT3 induced STAT3 inhibition, tumor cell death, and immune system activation through TLR9 signaling." (PMID 30340426, 2018). "STAT3 has been shown to play a critical function in promoting tumor growth, increasing survival of cancerous cells, promoting resistance to chemotherapy, and linked with an increased likelihood of AML relapse in patients." (PMID 30217007, 2018). "To date, the IL-10/STAT3 signaling pathway has been reported to play an important part in tumor progression, chemotherapy resistance and the anti-inflammatory response." (PMID 29497350, 2018). "We also investigated several reported PTK6 substrate candidates that link PTK6 kinase to oncogenic signaling in tumor cells, including Akt, Paxillin, STAT3/5, ERK1/2, p38, FAK and p130CAS." (PMID 29879184, 2018). "Metformin selectively inhibits STAT3 and restricts the growth of the tumour and induces apoptosis in TNBC cells." (PMID 29298879, 2018). "Nutraceuticals are also known to inhibit STAT3 activation pathway and to suppress survival of tumor cells." (PMID 30319623, 2018). "Our previous study showed that MSCs in the bone microenvironment promoted OS progression and protected tumor cells from drug-induced apoptosis through IL-6/STAT3 signaling." (PMID 29915309, 2018). "Stat3 is a transcription factor that regulates downstream target genes and plays a major role in tumor survival and oncogenesis." (PMID 29899555, 2018). "STAT3 is a transcription factor, contributing to diverse biological processes, including tumor cell proliferation, migration, invasion and survival." (PMID 29571296, 2018). "CCL2 induces accumulation and suppressive function of myeloid derived suppressive cells in tumor microenvironment in STAT3-dependent manner." (PMID 29541413, 2018). "In cancer, several of the cytokine mediators targeted by TB HDTs, trigger activation of the transcription factor, signal transducer and activator of transcription 3 (STAT3), which activates the signaling pathway mediating tumor-MDSC induction." (PMID 30298121, 2018). "Orthotopically transplanted grafts of GBM clones grown in three mice showed that STAT3 overexpression enhanced tumor-initiating properties, whereas STAT3 knockdown decreased tumor initiation." (PMID 30551687, 2018). "To directly determine the effect of activated STAT3 signaling on tumor growth we next stably transfected the IL-11Rα subunit into DLD-1 and SW48 CRC cells." (PMID 30572654, 2018). "TLR9/NF-κB signaling stimulated macrophages to release IL-6, which in turn jump-started proangiogenic and tolerogenic STAT3 signaling leading to tumor recurrence." (PMID 29541413, 2018). "Immunocytochemical analysis revealed that Foxp3 and Stat3 protein expression in the abdominal ascites were significantly reduced in PRP-treated tumor-bearing mice compared to control mice." (PMID 29735884, 2018). "IL-6 activates STAT3 and promote angiogenesis and tumor invasion through VEGF and matrix metalloproteinases expression." (PMID 30167088, 2018). "Other work has demonstrated that, once activated, STAT3 can modulate the tumour microenvironment, either directly or indirectly, by a plethora of means." (PMID 29875329, 2018). "It has been shown that ectopic expression of PIAS3 in cancer cells can suppress the transcriptional activity of STAT3 and inhibit tumour growth." (PMID 30054984, 2018).
tumor (continued). "Activation of STAT3, an IL-6-responsive transcription factor, was shown to induce tumor-promoting inflammation as well as activate canonical oncogenic pathways." (PMID 30389925, 2018). "It has been shown that STAT3 is an important regulator for many genes involved in survival, invasion, cycling, and apoptosis of tumor cells." (PMID 30518397, 2018). "STAT3 overactivation is known to contribute to tumor development by increasing cancer cell proliferation, survival, angiogenesis, and metastasis." (PMID 29921768, 2018). "The level of the STAT3 signalling inhibitor PIAS3 was increased in resveratrol-treated tumours of the LP group." (PMID 30176837, 2018). "While the specific composition of the tumor milieu differs between various cancers, tumor-derived factors commonly induce STAT3 signaling in myeloid cells infiltrating tumors." (PMID 29921770, 2018). "In summary, our findings suggest that targeting STAT3 in PSA producing ENZ-resistant tumors is a rational approach to reduce tumor burden." (PMID 30470788, 2018). "The intracranial tumour sizes, average life span, cell apoptosis and STAT3 signalling were evaluated by multiple experimental approaches in the tumour tissues harvested from both groups." (PMID 30176837, 2018). "The transcription of IL-10 in GAMs is mainly based on STAT3 signaling, which has been shown to be enhanced in tumor-derived GAMs as compared to normal microglia/macrophages." (PMID 29389898, 2018). "Cooperation between TLR4 signaling and STAT3 in promoting tumor-initiating stem-like cells in mouse liver was recently reported." (PMID 30034633, 2018). "We observed that STAT3 gene expression is higher in the tumours of cluster 2 when compared with the tumours of clusters 1 and 3 (one-way ANOVA p-value: 5.58 × 10−15)." (PMID 30375513, 2018). "First, we investigated the impact of including the in vitro TME on the basal activation of STAT3 in the tumor cells and compared it with the basal status during 2D monolayer culture." (PMID 29566069, 2018). "Inhibition of STAT3 activation has led to reduced tumor growth, decreased peritoneal dissemination, and diminished ascites production in a peritoneal ovarian tumor model." (PMID 29849942, 2018). "In terms of malignancies, STAT3 is the more important member of the STAT-family inducing tumor growth and immunosuppression." (PMID 30038723, 2018). "S1PR1 has key functions in tumor metastasis and angiogenesis, and maintains persistent STAT3 activation by regulating both tumor cells and tumor-infiltrating myeloid cells." (PMID 30377291, 2018). "Leptin activated the downstream Jak2/STAT3 signaling in LepR(+) tumor cells, which led to enhanced proliferation, survival and migration of tumor cells." (PMID 30013512, 2018). "The tumour tissues in the combination treatment group showed growth inhibition, extensive apoptosis, suppressed STAT3 expression and nuclear translocation and upregulated PIAS3 expression." (PMID 30176837, 2018). "Signal transducer and activator of transcription 3 (STAT3) is constitutively activated in numerous cancers and contributes to different processes involved in tumor progression such as cell proliferation, angiogenesis and metastasis." (PMID 29963272, 2018). "In particular, experiments in mice have shown that blocking STAT-3 activity in tumor cells abrogated the tumor-induced inhibition of DC maturation." (PMID 30477198, 2018). "Collectively, oncogenic G3BP1 serves as a signaling linkage molecule from upstream IL-6/EGF elicited stimulations to downstream STAT3 signaling, eventually contributing to promote tumor cell growth and metastasis in RCC." (PMID 29717134, 2018). "Inhibition of STAT3 activation by genetic and pharmacological approaches has been shown to suppress tumor growth and enhance the sensitivity of clinical drugs in various in vitro and in vivo models." (PMID 29576846, 2018).
tumor (continued). "Upon exposing tumor cells to various concentrations of essential oils, prepared cell lysates were investigated for the phosphorylation of STAT3 (Tyr705) and (Ser727) and performed by western blot analysis." (PMID 30190788, 2018). "When STAT-3 is activated, the tumor cell micro-environment is promoted through cell proliferation, angiogenesis, metastasis, and immune evasion." (PMID 29794990, 2018). "By releasing IL-6, MDSCs elicit STAT3 activation and invasive capabilities of BC cells, with subsequent increase in tumor and metastasis burden." (PMID 30200242, 2018). "As a key component of the JAK2/STAT3/Snail pathway, JAK2 is associated with macrophages on tumor infiltration involved in epithelial-mesenchymal transition." (PMID 29849669, 2018). "K685 acetylation can enhance the STAT3 transcriptional activity by increasing tyrosine phosphorylation and dimer stability, and K685-acetylated STAT3 was shown to silence the tumor suppressor genes by recruiting DNA methyltransferase 1 to their promoters." (PMID 30231582, 2018). "A further mechanistic study showed that tumor cell-intrinsic Tim-3 would promote HCC development by triggering auto-secretion of IL-6 and then accelerating tumor growth through the STAT3 signaling pathway." (PMID 30309387, 2018). "Studies with small-molecule inhibitors, acting on JAK2:STAT3 signaling, showed delayed tumor growth, which in some cases coincided with a TAM2 to TAM1 switch, an increase of MDSCs or was independent of TIM modulation." (PMID 30233579, 2018). "This indicates that IL-6 is not the major signaling pathway in the intestinal epithelium promoting intrinsic tumor growth via STAT3." (PMID 30591653, 2018). "Recent studies defined signal transducer and activator of transcription 3 (STAT3) as a potent regulator of gliomagenesis by inducing angiogenesis, host immunosuppression, tumor invasion, and anti-apoptosis." (PMID 29950561, 2018). "The study showed resveratrol treatment significantly suppressed tumor growth by inhibiting M2 polarization of TAMs and decreasing activation of signal transducer and activator of transcription 3 (STAT3) signaling." (PMID 29463044, 2018). "Aberrant and persistent activation of STAT3 can be mainly attributed to either oversupply of certain cytokines in tumor microenvironment or abnormal expression and dysfunctions of positive and negative regulators." (PMID 30143645, 2018). "IL-6/STAT3 signaling recruits and modulates function of tumor-infiltrating myeloid cell populations in cancer patients." (PMID 29541413, 2018). "Use of STAT3 inhibitors in tumor-bearing mice resulted in depletion of MDSCs in the spleen but not in tumors." (PMID 29675018, 2018). "Daily repeated treatments with NYT normalized STAT3 signaling in the skeletal muscle of tumor-bearing mice." (PMID 30555329, 2018). "Taken together, the role of STAT3 in enhancing tumor motility and increasing the EMT-like characteristics in irradiated/invasive GBM cells correlated with Slug expression." (PMID 30551687, 2018). "STAT3 promotes tumor growth and angiogenesis, inhibits immune responses, and promotes tumor invasion and metastasis." (PMID 29774125, 2018). "Inappropriate/persistent STAT3 activation is reported in a variety of clinical tumor samples, where it seems to drive multiple pro-oncogenic functions." (PMID 29914167, 2018). "The inhibition of STAT3 in both of the tumour subtypes resulted in alterations in the survival, proliferation, migration, and apoptosis, suggesting a potential role for therapeutically targeting STAT3." (PMID 29890775, 2018). "STAT3 constitutive activation has been shown to contribute to tumor development and progression, while IL-6/JAK pathway plays a crucial role in aberrant STAT3 signaling cascades." (PMID 29443735, 2018). "A previous study showed that CRC cell lines with a low STAT1/high STAT3 ratio presented faster tumor growth when they were xenografted into SCID mice." (PMID 30235866, 2018).
tumor (continued). "Originally, SP STAT3 was reported to sustain the tumor transformation of MEF cells downstream of Harvey rat sarcoma virus oncogene (H-RAS)." (PMID 30231582, 2018). "The inhibitory role of RKIP on STAT3 signaling and the consequent effects on metastasis initiation in vitro and in vivo have been also validated by additional studies on other tumor models." (PMID 30149591, 2018). "STAT3 has biological consequences in some malignancies and plays a critical role in activating tumor invasiveness outside the CNS." (PMID 30551687, 2018). "Uncontrolled/constitutive STAT3 activity is often detected in tumors of different types, where its role is mostly that of an oncogene, contributing in multiple ways to tumor transformation, growth, and progression." (PMID 30231582, 2018). "Stat3△IEC mice were almost completely inhibited from the formation of AOM-induced tumor while the mouse model with STAT3 hyperactivation (gp130Y757F) had even more severe tumor load after AOM/DSS challenge." (PMID 30498394, 2018). "Previous studies have also provided support for the combined targeting of HIF-1 and STAT3 under hypoxia for enhancing anti-tumor activity." (PMID 30347860, 2018). "Regulatory B-cells are expected to promote tumor growth by suppressing immune response through IL-10 and STAT3." (PMID 30383866, 2018). "ROS produced in the cancer cells can activate several transcription factors including activator protein-1, NF-kβ, and STAT3 which are essential in controlling cellular proliferation, tumor survival, and angiogenesis." (PMID 30622675, 2018). "STAT3 has been shown to be essential to maintain the tumor-initiating capacity, invasion capacity, cell survival, and cell cycle progression." (PMID 30200299, 2018). "SHP-1 has been reported as a tumor suppressor and a negative regulator of STAT3 in various cancer types." (PMID 29558404, 2018). "Then the high protein levels of STAT3 in tumour tissues were determined by western blot assay compared with adjacent tissues." (PMID 30134017, 2018). "Infiltrating immune cells produce cytokines that activate STAT3 and its target genes contributing to tumor‐promoting inflammation." (PMID 29907597, 2018). "Previous studies have shown that JAK2/STAT3 signaling regulates several important pathways in tumorigenesis, including cell cycle progression, apoptosis, tumor invasion, and metastasis." (PMID 29515107, 2018). "Conversely, inhibition of STAT3 reduced the expansion of MDSCs in tumor-bearing mice and reduced tumor progression." (PMID 30405034, 2018). "Aloin, which is derived from A. vera leaves, has been shown to possess anticancer effects too, as it inhibits tumor angiogenesis and growth via blocking STAT3 activation, therefore displaying a potential as drug candidate for cancer therapy." (PMID 30235891, 2018). "B(a)P upregulates STAT3 in MDA-MB-231 cell line; STAT3 plays an important role in supporting tumor growth." (PMID 30155724, 2018). "Tumor cell lines with constitutively activated STAT3 are dependent on its sustained activation, a phenomenon that has been termed “oncogene addiction”." (PMID 30217007, 2018). "In many cases, TAM-derived IL-6 and other cytokines activate STAT3 to promote tumor development by inducing proliferation and inhibiting apoptosis." (PMID 30271456, 2018). "In several tumor models including breast, liver, and pancreatic cancers, TAMs were shown to secrete growth factors to induce STAT3-mediated expression of stem cell-related gene expression pattern in cancer cells." (PMID 29921770, 2018). "Some studies support an NFκB and STAT3 crosstalk required for communication between tumor cells and their microenvironment." (PMID 29928478, 2018). "In this context, the effects of PD-L1 on clinical outcome need to be carefully analyzed with distinctive interpretation of its expression on tumor cells and immune cells with consideration of activation status of the STAT3-related signaling pathway." (PMID 30458835, 2018).
tumor (continued). "In particular, the persistent stimulation of IL-6 causes the activation of JAK2 and the subsequent phosphorylation/activation of STAT3, which contributes to tumor growth, chemo-resistance and metastasis." (PMID 29651140, 2018). "Alternatively, the activation of oncogenes, inactivation of tumor-suppressor genes, and other genetic events in the neoplastic cells can directly trigger STAT3 activation as part of an autocrine pathway." (PMID 30231553, 2018). "Downregulation of STAT3 mRNA expression has been reported to suppress the proliferation and migration of tumor cells." (PMID 30618745, 2018). "We have recently observed that STAT3 phosphorylation both at Tyr705 and Ser727 residues is increased in ccRCC tumor samples, and that Ser727 is an independent prognostic factor in ccRCC." (PMID 29464030, 2018). "STAT3 is induced in tumor cells under hypoxic conditions, which triggers tumor cell production of hypoxia inducible factor 1 alpha (HIF-1α) and VEGF; VEGF then acts on endothelial cells to promote cell proliferation and angiogenesis." (PMID 30200630, 2018). "Given the clear evidence of accumulation of ASO and suppression of STAT3 in the tumor microenvironment, it is likely that AZD9150 is exerting a positive immunomodulatory effect and clinically meaningful antitumor activity." (PMID 30446007, 2018). "Signal transducer and activator of transcription 3 (STAT3) is a transcription factor that plays a central role in tumour cell proliferation, survival, invasion, and immunosuppression." (PMID 30261753, 2018). "Next to STAT3, NF-κB is known to regulate the expression of many tumor-promoting genes, including VEGF, IL-6, TNF-α, and cyclooxygenase 2 (COX2), which support its crucial role in the activation of TAM2 in the TME." (PMID 30233579, 2018). "Thus, the balance between the two STAT3 isoforms, in turn dictated by the specific signals determining the tumor transformation and progression, and shaping the tumor microenvironment, is apparently crucial to determine the initial tumor transformation rates in inflammation-associated cancers." (PMID 30231582, 2018). "The present study showed that STAT3 signaling is activated in the skeletal muscle of tumor-bearing mice, and this activation is evident before the onset of skeletal muscle loss." (PMID 30555329, 2018). "RNA-sequencing and tumor microenvironment (TME) analysis demonstrate increased anti-tumor immune responses following Stat3 deletion in females and, conversely, elevated pro-tumor immune pathways in males." (PMID 30389925, 2018). "Bv8 induces CD11b+Gr-1+ cells in an autocrine and paracrine STAT3-dependent manner, and regulates CD11b+Gr-1+ cell-dependent tumor angiogenesis." (PMID 29621339, 2018). "Here, we report that Ganoderma lucidum extract (GLE), a medicinal mushroom with anticancer activity, acts on BCSCs in vitro and in TNBC pre-clinical animal tumor models by downregulating the STAT3 pathway." (PMID 30542507, 2018). "miR-320 (mostly miR-320a-3p) is considered to be a tumor suppressor miRNA, and several of its target genes/proteins that are involved in different physiological and tumor pathways (e.g., ß-catenin, Myc, STAT3) have been reported." (PMID 29535815, 2018). "An analysis of the staining pattern showed a clear difference between the three groups, with greater STAT3 S727 phosphorylation in the high-grade neoplasia compared with lower grade lesions." (PMID 29630659, 2018). "IL6, can prevent dendritic cell maturation, prime tumor-specific T-cells via signal transducer and activator of transcription 3 (STAT3) signaling, inhibit NF-κB binding activity, and inhibit C-C chemokine receptor type 7 (CCR7) expression." (PMID 29486723, 2018). "Tumor cells which lack STAT activation are more tolerant to small molecular inhibitors which block STAT3 signal pathway." (PMID 30577812, 2018). "A large number of independent studies confirm the potency of STATTIC as a direct STAT3 inhibitor and support its utility in combating tumor cells." (PMID 30283459, 2018).